RNY1P10 (RNY1 pseudogene 10)
Gene: Miscellaneous RNA gene on chromosome 16 (28,183,318 to 28,183,430, forward strand). Ensembl gene ENSG00000200138.
Homologues: Orthologues: chimpanzee Y_RNA (98% identical), macaque Y_RNA (91% identical), guinea pig Y_RNA (86% identical). Paralogues in human: RNY1P11 (87% identical), RNY1 (86% identical), Y_RNA (85% identical), Y_RNA (84% identical), Y_RNA (83% identical), RNY1P8 (82% identical), Y_RNA (82% identical), RNY1P12 (81% identical), RNY1P15 (81% identical), Y_RNA (81% identical), RNY1P5 (80% identical), Y_RNA (80% identical), and 93 more.